SIRT1 (sirtuin 1)
Diseases named in the same sentence as SIRT1 in open-access papers (continued):
Sharing a sentence is not in itself a finding about the gene and the disease.
atherosclerosis (continued). "Similarly, LincRNA-p21 shows promise as a therapeutic target for preventing atherosclerosis development through its regulation of the miR-221/SIRT1/PCSK9 axis." (PMID 40764605, 2025). "Interestingly, evidence from experimental studies indicates that estrogen, through the activation of SIRT1, has a protective effect on arteries, delaying their aging and the development of atherosclerosis." (PMID 41011644, 2025). "The miR-221/Sirt1 pathway: In the plasma of patients with atherosclerosis, in mouse models, and in ox-LDL-treated human aortic endothelial cells (HAECs), the expression of miR-221 is significantly elevated, whereas SIRT1 expression is decreased in atherosclerosis." (PMID 40563948, 2025). "SIRT1 plays a protective role in the development and progression of atherosclerosis." (PMID 40710369, 2025). "Because GAS5 can directly suppress miR-221, the lncRNA GAS5/miR-221/Sirt1 axis may modulate endothelial function during atherosclerosis." (PMID 40563948, 2025). "SIRT1 can also inhibit NF-κB signalling through deacetylation, reduce the expression of lectin-like oxLDL receptor-1 (Lox-1), and reduce the uptake of oxLDL, thus preventing the formation of atherosclerosis." (PMID 40507126, 2025). "This study focuses on how MICU1 regulates SIRT1 expression to influence atherosclerosis." (PMID 41329250, 2025). "SIRT1 is a key regulator of vascular homeostasis, exerting protective effects against oxidative stress, inflammation, endothelial dysfunction, lipid accumulation, and defective autophagy, which are consistent hallmarks of atherosclerosis." (PMID 41228388, 2025). "Natural activators of SIRT1, found mainly in plant foods, fruits, and vegetables, are in fact the molecular target that we have chosen to summarize in this review as potential beneficial agents in atherosclerosis." (PMID 41228388, 2025). "SIRT1, a member of the sirtuin family, increases nitric oxide (NO) production, reduces inflammation and oxidative stress, induces autophagy, and prevents senescence, all of which contribute to slowing the progression of atherosclerosis and vascular aging." (PMID 40507709, 2025). "Moreover, exercise-induced nitric oxide production plays a pivotal role in promoting cardiovascular health by enhancing vasodilation, reducing atherosclerosis, and activating protective enzymes like SIRT1." (PMID 39290329, 2024). "The present study provides new information on the potential of paeonol treatment in the prevention of VSMC senescence and atherosclerosis and suggests that paeonol may be a promising candidate as a SIRT1 agonist for the treatment of atherosclerosis." (PMID 38202844, 2024). "Oral administration of low-dose red wine significantly upregulates the expression of eNOS and SIRT1 in the aortas of hypercholesterolemic mice, suggesting that resveratrol may prevent atherosclerosis through the activation of the SIRT1 pathway." (PMID 39857372, 2024). "For instance, ginsenoside Rb1 exhibits the ability to modulate macrophage polarization, thereby mitigating atherosclerosis, Araloside C manipulates macrophage polarization via Sirt1-mediated autophagy, consequently lessening atherosclerosis, and danshensu promotes cholesterol efflux from RAW264." (PMID 38952541, 2024). "The results demonstrated that SIRT1 overexpression ameliorates endothelial dysfunction by activating the eNOS signaling pathway and suppressing endothelial inflammation, thereby attenuating atherosclerosis development." (PMID 39857372, 2024).
atherosclerosis (continued). "TMAO activates the cytosolic inflammasome NOD-Like Receptor Protein 3 (NLRP3), one of the key processes in the genesis of atherosclerosis and many chronic diseases, and accelerates the senescence of endothelial cells by inhibiting the activity of sirtuin 1 (SIRT1)." (PMID 38921674, 2024). "SIRT1 can regulate lipid metabolism and protect against atherosclerosis." (PMID 38304233, 2023). "Notably, the activation of SIRT1 hinders abnormal vascular smooth muscle cell proliferation and protects endothelial cells from damage, thus impeding the progression of atherosclerosis." (PMID 38186648, 2023). "Finally, SIRT1 reduces oxidative stress, which is one of the most important factors contributing to the development of atherosclerosis." (PMID 38139440, 2023). "The study concluded that G004 could be an effective anti-atherosclerosis agent stimulating SIRT1/eNOS." (PMID 38304233, 2023). "Overexpression of endothelial sirtuin 1 (SIRT1) may prevent atherosclerosis by improving vascular function." (PMID 37277452, 2023). "The findings of this study provide a new theoretical basis for the role of p65, SIRT1, and miR-200a-3p in oxidative stress and may provide a new strategy for the clinical prevention and treatment of atherosclerosis." (PMID 37874693, 2023). "The study indicates that targeting SIRT1, with its anti-inflammatory properties, may be a novel anti-inflammatory strategy in preventing atherosclerosis and CHD progression." (PMID 37730614, 2023). "The key role of SIRT1 in atherosclerosis is now established." (PMID 38304233, 2023). "The miR-200a-3p inhibitor can promote the expression of SIRT1 and inhibit pyroptosis, which may be important to prevent and treat atherosclerosis." (PMID 37874693, 2023). "In vitro and in vivo studies, as well as clinical trials in humans, have shown that SIRT1 activation might reduce or prevent atherosclerosis through various mechanisms." (PMID 38038821, 2023). "FOXO1 enhances the release of pro-inflammatory cytokines and controls macrophage oxLDL uptake and vascular calcification, consequently, senescent CD8+ CD28− T cells might slow atherosclerosis via SIRT1/FOXO1 decline." (PMID 38138958, 2023). "In vitro, we demonstrated that TMAO regulated ROS stimulation and AMPK and SIRT1 signaling to induce inflammation responses in VSMCs and HUVECs, which may contribute to promoting atherosclerosis." (PMID 36014845, 2022). "In conclusion, the role of SIRT1 in atherosclerosis has received extensive attention." (PMID 36581622, 2022). "However, the SIRT1-autophagy axis in ameliorating atherosclerosis needs to be further explored in subsequent studies." (PMID 36188570, 2022). "Taking into account that the downregulation of SIRT1 decreases the transcription of ABCA1, the activation of SIRT1 may be considered as a potential therapy for atherosclerosis and CVD." (PMID 34940525, 2021). "Thus, the purpose of this pilot study was to evaluate the potential utility of sirtuin 1, visfatin, and IL-27 as markers of early development of atherosclerosis or HF in young, asymptomatic women with T1DM and HD." (PMID 34439776, 2021). "The beneficial effects of SIRT1 in the vasculature protect against atherosclerosis." (PMID 34371836, 2021). "We studied the effects of berberine-induced TFEB activation via SIRT1 on autophagy and apoptosis in peritoneal macrophages and whether it protected against atherosclerosis." (PMID 33639613, 2021). "We did find an association between lipid parameters and IL-27 and sirtuin 1 levels in women with T1DM, which may lead to an increased risk of atherosclerosis." (PMID 34439776, 2021).
atherosclerosis (continued). "SS-31, a mitochondrial antioxidant, can enhance SIRT1 level and ameliorates leukocyte-endothelium interactions, inflammation, and oxidative stress in T2DM to prevent the risk of developing diabetic cardiovascular diseases, including atherosclerosis." (PMID 34071497, 2021). "SIRT1 and KLFs are important players in protecting against atherosclerosis." (PMID 33445491, 2021). "Thus, VSMC-derived SIRT1 is a critical modulator in the advanced stage of atherosclerosis, participating in plaque stability and vascular calcification." (PMID 33117155, 2020). "Sirtuin 1 (Sirt1), one of the sirtuins, deacetylates a variety of substrates and modulates angiogenesis and vascular tone, thereby may provide protective effect on atherosclerosis, cardiac ischaemic/reperfusion injury, and catecholamine‐induced cardiomyopathy." (PMID 32342656, 2020). "SIRT1 is known to reduce inflammation, possess anti-atherosclerosis activity, inhibit cardiomyocyte apoptosis and telomere shortening, resist myocardial oxidative stress damage and myocardial remodeling, maintain myocardial energy balance, and promote autophagy." (PMID 32082101, 2020). "Activation of SIRT1 was shown to have a protective effect on the process of atherosclerosis." (PMID 32796661, 2020). "Collectively, these results suggest that circ-Sirt1 is involved in the pathogenesis of vascular diseases, and it may act as a novel potential biomarker in the detection of patients with atherosclerosis." (PMID 30820544, 2019). "Based on these results, SIRT1 might be a potential target for researchers aiming to develop therapeutic interventions for vascular inflammation, including atherosclerosis." (PMID 31023999, 2019). "Conversely Sirt1 overexpression prevents these conditions as well as ageing-related pathologies such as atherosclerosis, Alzheimer’s disease and osteoporosis; it would be interesting to establish whether it does so by up-regulating ER signalling." (PMID 31746335, 2019). "The disruption of circ-Sirt1 may be a novel epigenetic mechanism in inflammatory phenotypic switching of VSMCs, and is a new biomarker and therapeutic target for atherosclerosis." (PMID 30820544, 2019). "Metformin protects endothelial cells from HG-induced premature senescence by restoring the HG-induced reduction in SIRT1 expression and attenuates atherosclerosis development by reducing the levels and translocation of dynamin-related protein (Drp1), preventing mitochondrial fragmentation." (PMID 30459620, 2018). "Additionally, Sirt1 activation induced by pulsatile flow prevents EC dysfunction and retards the progression of atherosclerosis." (PMID 28546854, 2017). "Based on this, we investigated whether Sirt1 inhibition, whose expression has been reported to inhibit atherosclerosis in vSMCs, also had an effect on SCA-1+ progenitor migration." (PMID 28757161, 2017). "Therefore, the protective effects of Sirt1 on vascular aging and atherosclerosis are proposed to act by increasing NO production, HERC2-mediated degradation of LKB1, anti-inflammatory activity, anti-oxidative stress and the induction of autophagy." (PMID 27744418, 2016). "Sirt1 plays a critical role in circadian rhythm and in atherosclerosis." (PMID 27631008, 2016). "Furthermore, the maintenance of SIRT1 homeostasis is fundamental to inhibit the harmful mechanisms of atherosclerosis such as the forkhead transcription factors (FoxOs)." (PMID 26885898, 2016). "What is the role of Sirt1 in vascular aging and atherosclerosis?" (PMID 27744418, 2016). "Furthermore, SIRT1 is recognized as a novel target for prohibiting the early stage atherosclerosis in the human endothelial cells." (PMID 26885898, 2016). "In addition, oxidative stress and oxidized low-density lipoprotein (oxLDL) increases DNA damage in VSMCs in atherosclerosis through reduced Sirt1 expression." (PMID 27744418, 2016).
atherosclerosis (continued). "Additionally, cyclin-dependent kinase 5 (CDK5)-mediated hyperphosphorylation of Sirt1 at Ser47 con-tributes to the development of endothelial senescence and atherosclerosis." (PMID 27744418, 2016). "In this review, we discuss regarding the role of Sirt1 activity in the pathogenesis of vascular aging and atherosclerosis, particularly focusing on the beneficial effects of Sirt1 against cellular senescence, inflammation, oxidative stress, autophagy deficiency and impairment of NO production." (PMID 27744418, 2016). "Thus, Sirt1 plays an important role in regulating inflammation in the settings of vascular aging and atherosclerosis." (PMID 27744418, 2016). "Recent studies have demonstrated the protective roles of SIRT1 in inflammation processes, vascular endothelial homeostasis and atherosclerosis, providing evidence that SIRT1 may play an important role in the pathogenesis of MI." (PMID 25706717, 2015). "SIRT1 upregulation with AMPK activation promotes autophagy that is necessary for endothelial cell protection during exposure to oxidized low density lipoproteins that can lead to atherosclerosis." (PMID 26064426, 2015). "Accumulating evidence has indicated that SIRT1 played an important role in protection against vascular aging and age-related vascular diseases, including inhibiting neointima formation and protecting against atherosclerosis." (PMID 25706717, 2015). "Sirt1 is considered a novel target in the prevention of atherosclerosis by regulating lipid metabolism, promoting endothelial survival and improving endothelial function, repressing vascular smooth muscle cell migration and proliferation and most importantly, inducing cellular autophagy." (PMID 24378473, 2014). "Taken together, these findings indicate that the negative regulatory mechanisms of NFAT by SIRT1 may contribute to its anti-inflammatory effects in atherosclerosis." (PMID 24859347, 2014). "Our results mainly provide preliminary evidence that Sirt1 potentially affects the efferocytosis of apoptotic macrophages via the activation of autophagy, which is useful in understanding the molecular mechanism and pathogenesis of atherosclerosis." (PMID 24378473, 2014). "SIRT1 seems to have protective properties against atherosclerosis." (PMID 25273948, 2014). "Since SIRT1 targets several proteins in distinct signaling pathways, modulation of SIRT1 activity alters the biological activity of entire signaling networks modifying disease progression, such as pathological angiogenesis or atherosclerosis." (PMID 25243179, 2014). "Many studies demonstrate that SIRT1 exhibits anti-inflammatory properties in vitro (e.g., fatty acid-induced inflammation), in vivo (e.g., atherosclerosis, sustainment of normal immune function in knock-out mice) and in clinical studies (e.g., patients with chronic obstructive pulmonary disease)." (PMID 23774840, 2013). "The class III HDAC SIRT1 has been also shown to play a protective role in atherosclerosis." (PMID 23551392, 2013). "Interestingly SIRT1 appears to counteract atherosclerosis by the regulation of tissue metalloproteinase 3 (TIMP3), an endogenous enzyme that antagonizes vascular inflammation." (PMID 23774840, 2013). "Therefore, SIRT1 plays a protective role in atherosclerosis in VSMCs by inhibiting the inflammatory events and thereby preventing atherosclerotic plaques formation." (PMID 23551392, 2013). "Because resveratrol consumption appears to reduce atherosclerosis, and activates SIRT1, SIRT1 may mediate at least part of this protective response." (PMID 24219792, 2013). "Indeed, in a mouse model of atherosclerosis, partial deletion of Sirt1 in bone marrow-derived macrophages promotes the development of atherosclerotic plaques." (PMID 23382833, 2013).
atherosclerosis (continued). "Since high levels of SirT1 have been found protective against atherosclerosis by several different studies as reviewed, high levels of SirT1 targeting miRNAs as observed in endothelial senescence might indeed contribute to disease progression." (PMID 24472232, 2012). "Although the specificity of available SIRT1 activators has beenquestioned recently, it islikely that SIRT1 activators may prevent atherosclerosis and other inflammatorydiseases by hindering pro-oxidative and inflammatory processes." (PMID 20606253, 2010). "In addition, SIRT1 suppresses the transcription of pro-inflammatory genes by modulating the nuclear factor kappa B (NF-κB) pathway, which contributes to the progression of inflammatory diseases, including atherosclerosis." (PMID 41228388, 2025). "What remains unclear about the role of SIRT1 in atherosclerosis is during the periods of hypoxia." (PMID 36952068, 2024). "Consequently, SIRT1 can protect against endothelial senescence and atherosclerosis." (PMID 38138958, 2023). "Thus, protection against vascular dysfunction and atherosclerosis in females may involve the activity of an oestrogen/sirtuin-1 axis." (PMID 37153459, 2023). "Consequently, SIRT1 activation could be a promising therapeutic strategy for treating arterial thrombosis and atherosclerosis." (PMID 38304233, 2023). "SIRT1 may be a therapeutic target for atherosclerosis, but further studies are needed to clarify the complex mechanisms of autophagy and ferroptosis in macrophages in the context of atherosclerosis." (PMID 35153792, 2022). "Other studies also showed that SIRT1 might prevent atherosclerosis by modulating eNOS activation." (PMID 35529430, 2022). "In summary, our present study showed that PEITC could play a protective role in the early stage of atherosclerosis progression by promoting cholesterol efflux from lipid‐laden macrophages, reducing lipid accumulation, and modulating the SIRT1‐NF‐κB signaling pathway." (PMID 34136191, 2021). "It has been shown that the activation of the AMPK/SIRT1 pathway could suppress the evolution of atherosclerosis by inhibiting endothelial cell oxidative stress and apoptosis, playing an effective and protective role in a variety of inflammatory-related disease." (PMID 32733639, 2020). "Additionally, we speculate that AsC attenuates foam cell formation and lessens atherosclerosis by modulating macrophage polarization via Sirt1-mediated autophagy." (PMID 31986489, 2020). "Thus, screening for potent selective Sirt1 activators has been the focus of research in the antiatherosclerosis drug development field, and more research into the mechanism by which Sirt1 activation affects atherosclerosis is imperative." (PMID 31986489, 2020). "Thus, SIRT1 might be a potential target to prevent the progression of vascular inflammatory diseases, including atherosclerosis." (PMID 31023999, 2019). "Furthermore, in vivo evidence from translational studies indicated that the dysregulation of SIRT1-SREBP-NLRP3 inflammasome may contribute to atherosclerosis." (PMID 31299012, 2019). "Metformin therapy may reduce inflammatory status and atherosclerosis by a direct SIRT1 induction." (PMID 30246793, 2018). "Whether SIRT1 prevents atherosclerosis in diabetic patients remains to be seen." (PMID 27123454, 2016). "Indeed, SIRT1 activity may be involved in the development of atherosclerosis and is thus a promising target for novel drugs against CVD and related diseases." (PMID 27123454, 2016). "Therefore, the activation of Sirt1 in vascular tissue, which includes ECs, monocytes/macrophages and VSMCs, may be a new therapeutic strategy against atherosclerosis and the increasing resistance to the metabolic disorder-related causal factors of CVD." (PMID 27744418, 2016). "However, it is still unclear whether Sirt1 in endothelial cells and VSMCs regulates autophagy and protects against atherosclerosis." (PMID 27744418, 2016).